MMP9 (matrix metallopeptidase 9)
Diseases named in the same sentence as MMP9 in open-access papers (continued):
Sharing a sentence is not in itself a finding about the gene and the disease.
herpes simplex encephalitis (1 paper, 2019). Herpes simplex virus encephalitis (HSE) is caused by the infection of the central nervous system by Herpes simplex virus (HSV) that could have a devastating clinical course and a potentially fatal outcome particularly with delay or lack of treatment. "In animal models of herpes simplex encephalitis, MMP-2 levels in CSF were high early in infection, as well as levels of MMP-9." (PMID 30777092, 2019).
herpesvirus infections (1 paper, 2010). "However, the association of MMP-9 with AOP-1 and SNAP-25 expression related to BoHV-5 neurological cases has never been described in association with herpesvirus infections." (PMID 20831786, 2010).
herpetic keratitis (1 paper, 2019). "MMP-9 has also been revealed to play an important role in angiogenesis and, specifically, in angiogenesis associated with herpetic keratitis." (PMID 31003493, 2019). "In a previous study, two plasmids encoding shRNA targeted against MMP-9 were effective to inhibit MMP-9 enzyme expression after intrastromal injection into the cornea of mice, stopping angiogenesis and decreasing the severity of herpetic keratitis." (PMID 31003493, 2019).
hip osteoarthritis (1 paper, 2023). "Masuhara K found that local and plasma MMP-3 and MMP-9 levels were significantly elevated in patients with rapidly destructive hip osteoarthritis, and he attributed the elevated blood levels to a large amount of MMP-9 produced in the synovial tissue of the hip." (PMID 36991363, 2023).
histiocytic sarcoma (1 paper, 2021). An aggressive malignant neoplasm with a poor response to therapy, usually presenting as stage III/IV disease. "Therefore, the virus-induced reduction of the MMP-9 expression might result in a decreased invasive potential of canine histiocytic sarcoma xenografts." (PMID 33808256, 2021).
Histiocytosis (1 paper, 2024). An excessive number of histiocytes (tissue macrophages). "Another marker connected with histiocytosis progression is MMP-9, also identified in CD207 cells from LCH lesions." (PMID 38342891, 2024).
HTLV infection (1 paper, 2022). "As HAM/TSP is an insidious complication of HTLV infection, long-term cohort studies are necessary to definitively validate the link between TNF and MMP-9 production in the context of HAM/TSP development." (PMID 36311773, 2022).
hydronephrosis (1 paper, 2020). Collection of urine in the renal pelvis that results in dilatation of the renal pelvis and calyces. "This study evaluates serum and urinary metalloproteinases MMP-1, MMP-2, and MMP-9 and tissue inhibitors of metalloproteinases TIMP-1 and TIMP-2 as potential biomarkers of ON in children with congenital unilateral hydronephrosis (HN) caused by UPJO." (PMID 32670438, 2020).
hyperaldosteronism (1 paper, 2015). Overproduction of aldosterone by the adrenal glands, which may lead to hypokalemia and/or hypernatremia. "Although we found a positive correlation between PAC and MMP-9/TIMP-1 ratio,hyperaldosteronism is known to be an independent risk factor in arterial hypertensionand, thus, in the process of arterial stiffening." (PMID 26039662, 2015).
Hypercalcemia (1 paper, 2025). An abnormally increased calcium concentration in the blood. "Clodronate, a drug used to treat hypercalcemia, has demonstrated inhibitory capacity on the activity of MMP-1, MMP-3, MMP-8, and MMP-9 by acting as a cation-chelator." (PMID 41002732, 2025). "Zoledronate, another drug used to treat hypercalcemia, suppresses MMP-2 and MMP-9 expression in PC3 prostate cancer cells, indicating that it is involved in the Ras/Raf/ERK and PI3K/AKT pathways, in addition to Discoin Domain Receptors (DDR) signaling." (PMID 41002732, 2025).
hyperkinetic disorder (1 paper, 2015). "So far, no studies have been conducted on the relationship of MMP-9 and cognitive function in children with attention deficit/hyperactivity disorder and hyperkinetic disorder (ADHD/HKD)." (PMID 24633733, 2015).
hypertensive emergencies (1 paper, 2020). "We cannot fail to highlight the strength of the findings of this study that compared the MMP-9 levels in hypertensive crisis to normotensive and controlled hypertensive subjects, and also among different presentations of hypertensive emergencies, which has not been evaluated by other studies." (PMID 32164582, 2020).
hypertensive heart disease (1 paper, 2020). Abnormal enlargement of the heart resulting from long-standing hypertension. "In accordance, alterations in the serum levels of MMP-9 and Tenascin-C variants reflecting myocardial tissue remodelling have been recently described in hypertensive heart disease." (PMID 32545310, 2020).
hypertriglyceridemia (1 paper, 2015). A laboratory test result indicating elevated triglyceride concentration in the blood. "It has also been previously demonstrated that MMP-9 level is correlated with blood triglycerides level while our data show that the serum MMP-9 level is higher in people with hypertriglyceridemia." (PMID 26692905, 2015).
hypoxic-ischemic encephalopathy (1 paper, 2021). "Elevated plasma MMP-9 is also associated with hypoxic-ischemic encephalopathy, correlating with severity of injury in human infants born at term." (PMID 34512648, 2021).
IgA pemphigus (1 paper, 2022). Immunoglobulin A (IgA) pemphigus is a group of newly characterized immune-mediated intraepidermal blistering skin diseases. "Our results for MMP-9 support the pathogenic role of infiltrating neutrophils and eosinophils in the pathogenesis of IgG/IgA pemphigus." (PMID 35625932, 2022). "Staining intensities of IL-8 and MMP-9 in the epidermis were significantly higher while that of C5a in the epidermis was lower in patients with IgG/IgA pemphigus (p < 0.05)." (PMID 35625932, 2022).
ileitis (1 paper, 2011). "Since both cytokines upregulate MMP-9 expression, it is possible that MIF regulates tissue remodeling in T. gondii-induced ileitis through a TGF-β/MMP-9 pathway." (PMID 21977228, 2011).
Incisional hernia (1 paper, 2022). An abdominal hernia that occurs at a site of weakness in the abdominal wall resulting from an incompletely-healed surgical wound. "Analysis of fascia from incisional hernia patients showed substantial elevations of MMP3 and MMP9, deregulation of ECM-altering enzymes, and alteration of collagen I/III ratios." (PMID 35439171, 2022).
incontinence (1 paper, 2022). "There is also in vivo data on the implication of ECM-degrading enzymes in incontinence, as increased MMP-2 and MMP-9 activity was reported in the vaginal wall after VD." (PMID 36742196, 2022).
infective endocarditis (1 paper, 2013). Infective endocarditis (IE) is an infection of the inner lining of the heart chambers (endocardium) and valves. "MMP-12 expression in cardiac valves taken from patients suffering from infective endocarditis has been shown to be elevated and human and animal studies have established the presence and activity of MMP-9 on cardiac-related remodeling." (PMID 23805173, 2013).
insulinoma (1 paper, 2009). "We showed, for the first time, that the APM human insulinoma derived cells, the only one presenting positive staining for E-cadherin, also displayed the lowest MMP-9 activity." (PMID 19545371, 2009).
internal carotid artery stenosis (1 paper, 2022). Carotid stenosis is a narrowing or constriction of the inner surface (lumen) of the carotid artery, usually caused by atherosclerosis. "The authors’ research has shown a significant increase in MMP2 and MMP9 activity and a significant increase in the concentrations of claudin-1 and occludin in the blood of patients undergoing the reconstruction of internal carotid artery stenosis." (PMID 35627746, 2022).
intrahepatic cholestasis (1 paper, 2022). A cholestasis characterized by impairment of the bile flow caused by obstruction located in the liver. "The inhibition of MMP-2 and MMP-9 activity in intrahepatic cholestasis of pregnancy ameliorated the biliary disease." (PMID 36551935, 2022).
invasive lobular carcinoma (1 paper, 2008). "It is certainly conceivable that the expression of activated MMP9 helps effect the characteristic, permeative, 'Indian file' growth pattern of invasive lobular carcinoma." (PMID 18954444, 2008). "However, one study did find overexpression in invasive lobular carcinoma relative to IDC, and noted that a single case of concurrent LCIS also showed MMP9 expression." (PMID 18954444, 2008). "Our study indicates that MMP9 RNA and protein is already present at the precursor (LCIS) stage of invasive lobular carcinoma, and raises the possibility that factors leading to its activation may play a role in the development of invasive disease." (PMID 18954444, 2008).
irritable bowel syndrome (1 paper, 2018). Irritable bowel syndrome (IBS) is a chronic functional condition of the lower gastrointestinal (GI) tract characterized by abdominal pain or discomfort and disordered bowel habit (diarrhea, constipation, or fluctuation between the two). "By measuring fecal MMP-9 levels, it was possible to distinguish UC from diarrhea predominant irritable bowel syndrome with 85% sensitivity and 100% specificity." (PMID 29530095, 2018).
keratoacanthoma (1 paper, 2024). A dome-shaped, rapidly growing skin lesion composed of well differentiated squamous cells. "A study comparing cSCC and keratoacanthoma samples revealed the presence of CD163+ macrophages and MMP-9+ cells only in cSCC samples." (PMID 38248804, 2024).
lagophthalmos (1 paper, 2022). "The aim of this study was to assess potential benefits usefulness of measuring tear film MMP-9 levels in patients with lagophthalmos after cerebellopontine angle tumor surgery." (PMID 36084126, 2022). "The aim of this study was to evaluate the possible usefulness of measuring tear film levels of MMP-9 in patients with lagophthalmos." (PMID 36084126, 2022). "Thus, the MMP-9 may also reflect the compliance of patients with the recommended treatment and may suggest that MMP-9 levels depend more on proper ocular surface lubrication than lagophthalmos severity." (PMID 36084126, 2022).
Langerhans cell histiocytosis (1 paper, 2024). Langerhans cell histiocytosis (LCH) is a systemic disease associated with the proliferation and accumulation (usually in granulomas) of Langerhans cells in various tissues. "For MMP9, Langerhans cell histiocytosis, conditioned medium study, and CML study showed highest values." (PMID 38803919, 2024).
large cell carcinoma (1 paper, 2020). A malignant epithelial neoplasm composed of large, atypical cells. "This may be due to the low sample size of large cell carcinoma (4 patients) of whom three patients (65%) had high scores for MMP-9 expression." (PMID 32944046, 2020).
Left ventricular diastolic dysfunction (1 paper, 2021). Abnormal function of the left ventricule during left ventricular relaxation and filling. "Alterations in MMP9 and TIMP1 enzymes were found to be significant indicators of greater degrees of asymptomatic left ventricular diastolic dysfunction." (PMID 34957261, 2021).
leukodystrophy (1 paper, 2021). Leukodystrophies are a group of rare, progressive, metabolic, genetic diseases that affect the brain, spinal cord and often the peripheral nerves. "In this leukodystrophy, increased MMP9 expression in the perilesional WM was found in microglia, astrocytes and endothelial cells." (PMID 34082828, 2021).
Lissencephaly (1 paper, 2025). A spectrum of malformations of cortical development caused by insufficient neuronal migration that subsumes the terms agyria, pachygyria and subcortical band heterotopia. "Recently, a human neural organoid model of lissencephaly showed altered stiffening and disorganization of ECM upon LIS1 mutation, which was reverted upon MMP9 treatment." (PMID 40678520, 2025).
lobular neoplasia (1 paper, 2008). A spectrum of non-invasive neoplastic lesions that arise from the terminal ductal lobular units of the breast. "MMP9 therefore represents an interesting therapeutic and chemopreventive target for patients with lobular neoplasia, both invasive and non-invasive." (PMID 18954444, 2008).
lung adenoma (1 paper, 2020). A benign, well circumscribed epithelial neoplasm that arises from the bronchus or the lung parenchyma. "In accordance with the elevated MMP9 expression, the expression of CD31 was observed to be increased in PRDX4 Tg tumor tissue, indicating a higher density of microvessels which benefits the development of lung adenoma in mice." (PMID 33456675, 2020).
lymphadenitis (1 paper, 2022). Acute or chronic inflammation of one or more lymph nodes. "MMP-9 is associated with the onset of lymphadenitis in patients with CAC, and is significantly up-regulated before the onset of lymphadenitis in these patients." (PMID 36776395, 2022).
Lymphadenopathy (1 paper, 2023). Enlargement (swelling) of a lymph node. "Linear regression showed that presence of metastasis in the liver is significantly associated with MMP-9 values after procedures (Beta = −0.911, p = 0.049) when adjusted for baseline MMP-9 values, presence of lymphadenopathy, CRP, and glucose." (PMID 36837539, 2023).
lymphangioleiomyomatosis (1 paper, 2021). A multifocal neoplasm with perivascular epithelioid cell differentiation affecting almost exclusively females of child-bearing age. "In lymphangioleiomyomatosis (LAM), a pulmonary rare disease, MMP-2 and MMP-9 have been detected at high levels in serum and urine." (PMID 34944575, 2021).
lymphoid tumor (1 paper, 2000). "The currentstudy was designed to determine the expression and production of MMP-2 (gelatinase A)and MMP-9 (gelatinase B) by human lymphoid tumor cells." (PMID 11097203, 2000).
malnutrition (1 paper, 2023). Inadequate nutrition resulting from poor diet, malabsorption, or abnormal nutrient distribution. "MMP-9 is a biomarker associated with pathological progression of muscle injury and malnutrition, and increased expression of MMP-9 may be involved in muscle inflammatory responses." (PMID 37928155, 2023).
malocclusion (1 paper, 2025). "Candidate genes such as COL1A2, matrix metalloproteinases (MMP-1, MMP-9), and muscle-related genes (ACTN2, ACTN3) have been implicated in craniofacial morphology and malocclusion risk." (PMID 41153339, 2025).
marginal zone B cell lymphoma (1 paper, 2016). "However, others have reported anetoderma arising from marginal zone B cell lymphoma in which MMP-9, but not MMP-2 or MMP-12, is expressed in infiltrating lymphocytes, suggesting some degree of pathogenic heterogeneity for this disease." (PMID 28116317, 2016).
memory (1 paper, 2013). The activities involved in the mental information processing system that receives (registers), modifies, stores, and retrieves informational stimuli. "MMP-9 (gelatinase B)-deficient mice displayed memory deficits." (PMID 23696812, 2013).
Microcystic Meningioma (1 paper, 2015). A WHO grade I meningioma characterized by the presence of intercellular microcystic spaces that contain mucinous fluid. "The results suggested that the increased ratio of MMP-9 to TIMP-1 might be associated with the formation of microcysts and peritumoral edema in microcystic meningioma." (PMID 25821815, 2015).
middle ear infections (1 paper, 2025). "The relationship between high expression levels of MMP-9 and the severity of chronic middle ear infections and the tendency to tympanosclerosis should be investigated." (PMID 40468054, 2025).
mood disorder (1 paper, 2022). A cognitive disorder a disturbance in which the person's mood is hypothesized to be the main underlying feature. "Serum MMP-9 is found to be increased in MDD patients, while MMP-2 is decreased in MDD patients, indicating the involvement of MMP-2 and MMP-9 in mood disorders." (PMID 35996194, 2022).
morphine dependence (1 paper, 2012). Strong dependence, both physiological and emotional, upon morphine. "Sustained morphine exposure also induces MMP-9 up-regulation in the spinal cord, leading to opioid-induced withdrawal responses that might be associated with morphine dependence." (PMID 22444868, 2012).
motor neuron disease (1 paper, 2024). "In addition, in several motor neuron disease models, reducing MMP9 has been found to protect neurons and delay the loss of motor function." (PMID 39635981, 2024).
Multiple Organ Failure (1 paper, 2020). A progressive condition usually characterized by combined failure of several organs such as the lungs, liver, kidney, along with some clotting mechanisms, usually postinjury or postoperative. "The study hypothesis was that the levels of MMP-9 and TIMP-1 were elevated in patients hospitalised in the ICU due to multiple organ failure (MOF) and that the severity of organ dysfunction and treatment outcomes were correlated with the levels of MMP-9 and TIMP-1." (PMID 32190734, 2020).
muscular atrophy (1 paper, 2023). The loss of muscle tissue due to inactivity or disease. "released that MMP-9 activation in ALS serum occurs prior to the onset of muscular atrophy or peripheral nerve degeneration, suggesting that MMP-9 activation is not merely a byproduct of nerve injury." (PMID 37662922, 2023).
Myalgia (1 paper, 2020). "Finally, we did not record any difference in the expression of MMP-2 and MMP-9 in patients who developed myalgia during statin treatment." (PMID 32111073, 2020).
Mycoplasma pneumonia (1 paper, 2017). "In addition, the MVD group exhibited more Mycoplasma pneumonia, which positively correlated with gelatinase MMP9, an enzyme that participates in collagen degradation, as reported by other authors." (PMID 28431520, 2017).
myeloproliferative disorder (1 paper, 2023). A clonal hematopoietic stem cell disorder, characterized by proliferation in the bone marrow of one or more of the myeloid (i.e., granulocytic, erythroid, megakaryocytic, and mast cell) lineages. "Increased plasma endostatin and MMP9 in ET have not been reported previously, and further studies are necessary to define their possible roles in angiogenesis in myeloproliferative disorders." (PMID 37051288, 2023).
myxofibrosarcoma (1 paper, 2014). A malignant fibroblastic neoplasm arising from the soft tissue. "In the MTAP-deficient xenografts and myxofibrosarcoma specimens, MMP-9 overexpression was present in the tumor cells and extracellular stroma and associated with increased microvessel density." (PMID 25426549, 2014). "In the luciferase reporter assay, the antiangiogenic effect of MTAP was determined to primarily link to the transcriptional repression of MMP-9, ultimately attenuating mRNA and protein expression in the myxofibrosarcoma cells." (PMID 25426549, 2014). "Recently, we reported that the antiangiogenic function of ASS1, a rate-limiting enzyme converting citrulline into arginine in the urea cycle, was also attributable to the inhibition of ASS1 on MMP-9 expression in myxofibrosarcomas." (PMID 25426549, 2014). "Analogously, MMP-9 overexpression in the ASS1-deficient and MTAP-deficient myxofibrosarcomas is likely mediated by overexpressed ODC, which converges growth-promoting signals to orchestrate transcriptional regulation." (PMID 25426549, 2014). "Real-time RT-PCR showed decreased expression of MMP-9 mRNA in both MTAP-reexpressing myxofibrosarcoma cell lines." (PMID 25426549, 2014). "These exemplified the oncogenic role of MMP-9 in myxofibrosarcoma pathogenesis and corresponded with previous reports on its associations with aggressiveness in various cancer types." (PMID 25426549, 2014).
nasopharyngeal neoplasm (1 paper, 2021). A benign or malignant neoplasm affecting the nasopharynx. "Presence of melatonin inhibited TPA-induced cell motility by regulating the matrix metalloproteinase-9 (MMP-9) expression in nasopharyngeal neoplasm cells." (PMID 34721756, 2021).
neovascular glaucoma (1 paper, 2024). "In neovascular glaucoma due to RVO, the VEGF-VEGFR2 pathway suppresses occludin, causing damage to intercellular tight junctions, and activates MMP-9, resulting in the destruction of the blood–retinal barrier." (PMID 39272767, 2024).